LIF (LIF interleukin 6 family cytokine)
Diseases named in the same sentence as LIF in open-access papers (continued):
Sharing a sentence is not in itself a finding about the gene and the disease.
breast carcinoma (continued). "In conclusion, our results clarified that during the communication between CAAs and breast cancer cells, CAA-derived LIF promotes breast cancer cell migration and invasion by activating the Stat3 signal." (PMID 35280694, 2022). "In this review, we summarize the role of the IL-6 cytokine family—specifically IL-6 itself, LIF, OSM, and IL-11—as relevant players during breast cancer progression." (PMID 35163731, 2022). "After neutralizing the LIF of CAA-CM by using LIF neutralizing antibodies, CAA's promotion of breast cancer cell migration and invasion was inhibited." (PMID 35280694, 2022). "Our results indicated that LIF plays an important role in CAA-mediated migration and invasion of breast cancer cells by regulating the activation of Stat3." (PMID 35280694, 2022). "The majority of breast cancer metastases are lytic; breast cancer cells produce TNF-A, IL-8, IL-11, IGF1, LIF (leukemia inhibitory factor), lysyl oxidase, RANK ligands, and PTHrP." (PMID 36230523, 2022). "In breast cancer, CAFs secreted soluble factors such as activin A, insulin growth factor (IGF)-1, and leukemia inhibitory factor (LIF), all of which enhanced CSC proliferation and self-renewal via the activation of hedgehog signaling." (PMID 35814444, 2022). "Inhibition of the LIF/LIFR/JAK1 pathway or inhibition of BRD4, which increases LIFR transcription, increases sensitivity of breast cancer cell lines, xenografts, and allografts to histone deacetylase inhibitors." (PMID 35204717, 2022). "In spite of the data indicating the pro-oncogenic role of LIF, a whole genome RNAi screening identified LIFR as a mammary tumor suppressor." (PMID 35163731, 2022). "Breast cancer cells T47D and MDA-MB-231, treated with LIF injected into mice, induced lung and neck metastasis compared to the control." (PMID 34947829, 2021). "Overall, the findings in both PDAC and NPC suggest that the relationship between LIF-LIFR signaling, YES-YAP activity and the Hippo pathway are significantly more nuanced than originally described in breast cancer models." (PMID 34395259, 2021). "Another pattern seen is the propensity for LIF signaling to result in migration and metastasis, something seen in its close relative OSM and IL-6 in multiple cancers, most notably, breast cancer." (PMID 34395259, 2021). "We showed that breast cancer cells stimulated CAFs to secrete LIF, and in turn, the CAF-derived LIF regulates cancer stemness in breast cancer cells." (PMID 34947829, 2021). "After confirmation of LIF secretion by CAFs, to evaluate the effect of LIF cytokine on CSC plasticity, we treated breast cancer cells with CAF-CM." (PMID 34947829, 2021). "Our study showed that CAFs secrete LIF to stimulate the LIF receptor on breast cancer cells and thus activate the LIF/LIFR signaling pathway, which promotes breast cancer stemness in vitro." (PMID 34947829, 2021). "Even the case for STAT3 being a driver of metastasis and tumor growth in breast cancer has been challenged, as there have been studies that have shown both LIF and OSM suppressing tumor growth and metastasis via STAT3 in breast cancer cell lines." (PMID 34395259, 2021). "It was observed that Nanog and Oct4 expression, which was substantially increased after LIF or CAF-CM treatment, was decreased following exposure to the LIFR inhibitor antibody in both breast cancer cell lines." (PMID 34947829, 2021). "LIF: The LIF receptor (LIFR) was identified as a breast tumor suppressor by an shRNA screen and shown to function as a breast cancer lung metastasis suppressor by a second laboratory." (PMID 32023849, 2020). "In this study, we investigated the consensus of LIF and LIFR immunization on the growth of mouse mammary tumors." (PMID 32651426, 2020). "Another regulator of stem cell activity, leukemia inhibitory factor (LIF), was shown to promote tumor dormancy of breast cancer cells in the bone." (PMID 30258818, 2018).
breast carcinoma (continued). "Consistent with these previous reports, analysis in 2 different breast cancer datasets from Oncomine (GSE14548 and GSE9014) showed that LIF mRNA levels were elevated in invasive breast carcinomas compared with the normal breast tissues." (PMID 26716902, 2016). "The expression levels of LIF are much higher in MDA-MB-231 and HS578T cells that display higher metastatic abilities compared to less metastatic breast cancer cells, including MCF7, MDA-MB-468, SK-Br-3, T47D and BT474 cells." (PMID 24553191, 2014). "Taken together, these results demonstrate that LIF activates the AKT-mTOR pathway, which in turn promotes tumorigenesis and metastasis of breast cancer." (PMID 24553191, 2014). "We found that LIF activates the AKT-mTOR signaling pathway to promote tumorigenesis and metastasis of breast cancer." (PMID 24553191, 2014). "When LIF binds to this complex, it activates a cascade of signaling pathways that include STAT, AKT, and mTOR, all of which are involved in the progression of breast cancer." (PMID 40075639, 2025). "On the other hand, high LIFR expression has been correlated with tumor progression, and inhibition of LIFR improves histone deacetylase (HDAC) inhibitor efficacy, suggesting that further research is needed to elucidate the role of LIF and LIFR in breast cancer." (PMID 40507264, 2025). "The lower levels of cytokines LIF, MCP-1, and KC in the CIRP/PyMT supernatants likely played a role in the decreased tumor growth observed, as these cytokines are all known to maintain the pro-tumor microenvironment in breast cancer." (PMID 38397942, 2024). "Breast cancer cells that reside in the bone ECM induce osteoclast formation by releasing tumor necrosis factor-α (TNF-α), parathyroid hormone-related peptide (PTH-rP), prostaglandin E2 (PGE2), interleukins, and leukemia inhibitory factor (LIF)." (PMID 38317174, 2024). "Small-molecule inhibitors that target LIF/LIFR, such as EC359 and EC330, were used to treat ovarian cancer (OCa), breast cancer, and endometrial cancer (ECa), which inhibited tumor development in OCa cells, ECa cells, and breast cancer MCF7 cells." (PMID 38672566, 2024). "We found that human breast cancer does not have the same cytokine profile as PyMT-B6 as it only overexpresses IL-1α but not LIF or G-CSF, while human colon cancer was the only cancer to overexpress all 3 cytokines." (PMID 37134077, 2023). "Among these different CAF subtypes, iCAFs are reported to have a particular effect on chemoresistance in breast cancer patients, probably due to their high secretion of cytokines involved in therapy resistance, such as CXCL1–3, CCL2, CSF3, CXCL10, IL1β and LIF." (PMID 36710348, 2023). "Moreover, the interaction between CAAs and breast cancer cells involves a positive feedback loop between the cytokine leukemia inhibitory factor (LIF) and CXCL subfamily chemokines, which promotes breast cancer invasion and metastasis." (PMID 36670988, 2023). "Importantly, we found that breast cancer-derived CXCL1-3 and CXCL8 bind to the receptor CXCR2 and activate the ERK1/2 signaling pathway to initiate the expression of LIF by activating transcription factors NF-κB and Stat3 in CAAs in paracrine manner." (PMID 35280694, 2022). "Furthermore, breast cancer cells MCF7 (CD24+/CD44−) and MDA-MB-231 (CD24−/CD44+) were continuously exposed to exogenous LIF and analyzed for CD24/CD44 expression variations over time." (PMID 34947829, 2021). "LIF binds to LIF receptor (LIFR), which has been shown to be downregulated in patients with breast cancer bone metastasis.Of note, several key bone cells including osteoblasts, osteoclasts, chondrocytes and adipocytes secrete LIF and also express corresponding receptors." (PMID 33809315, 2021). "Interestingly, the restoration of LIFR in highly aggressive MDA-MB-231 cells by treatment with a histone deacetylase inhibitor restores STAT3 signaling downstream of LIF:LIFR, which has been proposed to promote drug resistance by breast cancer cells." (PMID 32023849, 2020).
breast carcinoma (continued). "Moreover, osteoblasts and osteocytes also secrete leukemia inhibitory factor (LIF), and the activation of LIF receptors present in breast cancer cells is shown to maintain them in a dormant state." (PMID 33162934, 2020). "Additionally, we studied 4 more factors that were pointed out by the cytokine array in the current study, but did not pass all our selection criteria, and appeared in the METABRIC breast cancer database: DKK1, IL-6, LIF, and M-CSF." (PMID 33158447, 2020). "Other examples proving the molecular similarity between dormant DCCs and CSCs include the interleukin 6 (IL-6) cytokine leukemia inhibitory factor (LIF)-LIF receptor (LIFR) axis, which appears to have a role in preserving both dormancy and cancer stemness, at least in the breast cancer setting." (PMID 33193295, 2020). "We next assessed whether such a LIF-dependent gene signature is also shared by the CAF isolated from tissue biopsies of patients with head and neck, lung or breast carcinomas." (PMID 27901489, 2017). "On the other hand, dormancy induction in bone marrow has been attributed to the action of stromal BMP‐7, transforming growth factor‐β2 (TGF‐β2), and leukemia inhibitory factor (LIF) in prostate cancer, head‐and‐neck squamous cell carcinoma, and breast cancer, respectively." (PMID 28085223, 2017). "While the overexpression of LIF has been observed in several types of cancers including breast cancer, the role of LIF in cancer is not well-understood." (PMID 24553191, 2014). "To analyze the biological activity of LIF on mouse mammary tumor and non-tumor cells, we evaluated the effect of this cytokine on the survival of HC11, TPC and LM3 cells." (PMID 17925034, 2007). "In mammary tumors, to our knowledge, no report has yet been made linking LIF expression to Stat3 activation." (PMID 17925034, 2007). "Finally, an ex vivo correlation has been established between the expression of iCAF marker LIF and myCAF marker αSMA with breast cancer tissue sections from patients with or without obesity." (PMID 36710348, 2023). "Previously, we found high expression of LIF in CAA but not in adipocytes, indicating that this phenomenon may be caused by breast cancer." (PMID 35280694, 2022). "Furthermore, we verified that adipocytes enhanced lung metastasis of breast cancer cells, and the combination of EC330 (targeting LIF) and SB225002 (targeting C-X-C motility chemokine receptor 2 (CXCR2)) significantly reduced lung metastasis of breast cancer cells in vivo." (PMID 35280694, 2022). "It has been reported that LIF oncogenic activity is mediated by STAT3 phosphorylation and translocation to the nuclei, and our group has reported that activation of this transcription factor in mammary tumor cells is dependent on paracrine/autocrine LIF secretion." (PMID 35163731, 2022). "Our data further indicate that blocking the LIF/LIFR signaling pathway could decrease cancer stemness in breast cancer cells, which points to a potential clinical application of targeted therapy using a LIFR inhibitor for breast cancer cells." (PMID 34947829, 2021). "However, no linkage has yet been made between LIF expression and Stat3 activation in mammary tumors." (PMID 17925034, 2007). "Consequently, the IL-7/HGF/LIF/VEGF cluster has been identified as a functional module that orchestrates multiple processes, including development, angiogenesis, stem cell maintenance, and the establishment of an immunosuppressive phenotype within the breast cancer microenvironment." (PMID 41597220, 2026). "Furthermore, the promoting effect of LIF on tumorigenesis and metastasis of breast cancer is independent of ER status; similar effects of LIF were observed in both ER-positive breast cancer cells (MCF7 and T47D) and ER-negative breast cancer cells (MDA-MB-231)." (PMID 24553191, 2014).
breast carcinoma (continued). "While OSM, LIF, and IL-6 can induce STAT3, AKT, and ERK signaling in breast cancer cells, in the absence of studies using combinations of STAT3, AKT, and ERK inhibitors, it is difficult to determine which is the dominant downstream mediator." (PMID 32023849, 2020). "However, zebrafish are not mammalian, so some important pathways in breast cancer tumor development are absent, including BRCA1, p16 (CDKN2A), Leukemia Inhibitory Factor (LIF), oncostation M (OSM) and interleukin 6 (IL6)." (PMID 34123857, 2021). "Additionally, they found that breast cancer cells which aggressively colonize the lung also lack a functional LIFR and do not respond to LIF in vitro." (PMID 28629464, 2017). "However, since these studies made use of the MDA-MB-231 breast cancer cell line, which several groups have shown does not express a functional LIFR, it is unclear how LIF may stimulate the migration and invasion of these cells in vitro." (PMID 32023849, 2020).
pancreatic cancer (41 papers, 2014 to 2025). "Recent studies in pancreatic cancer have also implicated Ras mutations in the upregulation of LIF signaling, which further promotes tumor cell survival and therapy resistance." (PMID 41154625, 2025). "We employed multi‐omics analysis combined with cellular and animal experiments to examine the association between CTHRC1 and the LIF/STAT3 pathway in pancreatic cancer clinical specimens." (PMID 40751418, 2025). "LIF expression is associated with shorter overall survival and recurrence-free survival in pancreatic cancer patients." (PMID 35159011, 2022). "Given that LIF has been implicated in EMT in pancreatic cancer, we sought to determine whether chemo/anti-LIF/anti-PD-L1 affects EMT in our model." (PMID 39857986, 2025). "Since LIFr expression was increased in melanoma when compared to nevi, and LIF signaling is linked to proliferation of breast, kidney, prostate and pancreas carcinoma cells, we hypothesized that LIFr expression affects melanoma cell growth." (PMID 26329521, 2015). "Also, two recent studies have implicated LIF in the progression of pancreatic cancer." (PMID 34779136, 2022). "LIF is an important component of the IL‐6 cytokine family; studies have shown that the expression level of LIF in pancreatic cancer tissue is significantly increased compared with normal pancreatic tissue, and CAFs are the main cell source of LIF." (PMID 40751418, 2025). "The results showed that the proliferation and migration of pancreatic cancer cells were significantly inhibited after adding the LIF inhibitor, and the inhibition was significant as the inhibitor concentration increased." (PMID 40751418, 2025). "For instance, LIF acts in a paracrine manner in Ras/Raf-mutant pancreatic cancer to support tumor progression, and to promote stemness and invasion in pancreatic cancer." (PMID 41154625, 2025). "Emerging evidence from pancreatic cancer models shows that stromal-derived LIF acts in a paracrine manner to promote tumor progression, and that LIFR blockade enhances response to chemotherapy." (PMID 41154625, 2025). "The results showed that the proliferation and migration of pancreatic cancer cells were significantly inhibited after adding the LIF inhibitor, and the inhibitory effect was also significantly enhanced as the inhibitor concentration increased." (PMID 40751418, 2025). "CTHRC1 in CAFs promotes the growth and metastasis of pancreatic cancer cells through the LIF/STAT3 signaling pathway." (PMID 40751418, 2025). "Then, we cocultured CAFs‐CM overexpressing CTHRC1 with pancreatic cancer cells and added the LIF inhibitor EC330 at various concentrations." (PMID 40751418, 2025). "We initially detected significantly higher LIF expression in CAFs compared to pancreatic cancer cell lines and HPSCs." (PMID 40751418, 2025). "We found that LIF expression was most significantly higher in CAFs, with very low expression in pancreatic cancer cells and HPSCs." (PMID 40751418, 2025). "In mechanistic studies, RNA sequencing revealed that CTHRC1 promotes the proliferation and migration of pancreatic cancer cells through the LIF‐mediated STAT3 axis." (PMID 40751418, 2025). "We also examined the effect of adding the LIF inhibitor to CAFs‐CM on the proliferation and migration of pancreatic cancer cells using CCK‐8, colony formation, and Transwell migration assays." (PMID 40751418, 2025). "The results showed that the phosphorylation level of STAT3 in pancreatic cancer cells was significantly downregulated after adding the LIF inhibitor, and the downregulation became more significant as the inhibitor concentration increased." (PMID 40751418, 2025). "The enhanced LIF secretion has been reported to be involved in inducing cancer cell stemness via circFARP1, thus promoting gemcitabine resistance in pancreatic cancer." (PMID 40416597, 2025).